ENPP5 (ectonucleotide pyrophosphatase/phosphodiesterase family member 5)
Description:
Can hydrolyze NAD but cannot hydrolyze nucleotide di- and triphosphates. Lacks lysopholipase D activity. May play a role in neuronal cell communication.
Synonyms: NPP-5; NPP5
Tractability: Antibody: UniProt places it where antibodies can reach, with high confidence; UniProt predicts a signal peptide or a membrane-spanning region; its Gene Ontology location is reachable by antibodies, with medium confidence. PROTAC: its protein half-life has been measured.
Gene: Protein-coding gene on chromosome 6 (46,158,482 to 46,171,113, reverse strand). Ensembl gene ENSG00000112796.
Subcellular location: Secreted; Membrane
Subcellular location (Human Protein Atlas): Cytosol; Nucleoplasm
Gene Ontology:
Molecular function: NAD+ diphosphatase activity; zinc ion binding; hydrolase activity
Biological process: cell communication
Cellular component: plasma membrane; extracellular region; membrane
Genetic constraint (gnomAD): Loss-of-function variants: 31 observed, 37.6 expected, observed/expected ratio (o/e) 0.82, 90% interval 0.62 to 1.11. The upper end of that interval is the gene's LOEUF score, 1.11, which puts it in group 4 of 6, group 1 being the genes least tolerant of losing a copy. Missense variants: 544 observed, 601.65 expected, observed/expected ratio (o/e) 0.9, 90% interval 0.84 to 0.97. Synonymous variants: 197 observed, 207.49 expected, observed/expected ratio (o/e) 0.95, 90% interval 0.85 to 1.07.
Homologues: Orthologues: chimpanzee ENPP5 (99% identical), macaque ENPP5 (96% identical), dog ENPP5 (87% identical), rabbit ENPP5 (87% identical), pig ENPP5 (86% identical), guinea pig ENPP5 (84% identical), mouse Enpp5 (82% identical), rat Enpp5 (82% identical), zebrafish enpp5 (52% identical), Caenorhabditis elegans C01B10.9 (25% identical), Caenorhabditis elegans enpp-1 (24% identical), Caenorhabditis elegans C27A7.3 (23% identical). Paralogues in human: ENPP4 (43% identical), ENPP3 (31% identical), ENPP7 (30% identical), ENPP1 (30% identical), ENPP6 (29% identical), ENPP2 (26% identical).
Diseases named in the same sentence as ENPP5 in open-access papers:
ENPP5 is named in the same sentence as 12 diseases in open-access papers, as found by Europe PMC text mining. Sharing a sentence is not in itself a finding about the gene and the disease. The quoted sentences say what the papers report.
Insulin resistance (3 papers, 2019 to 2024). Increased resistance towards insulin, that is, diminished effectiveness of insulin in reducing blood glucose levels. "Ectonucleotide pyrophosphatase/phosphodiesterase 5 (ENPP5), SLC38A1, and TM4SF1 are novel biomarkers for the development of insulin resistance." (PMID 30678306, 2019). "ENPP5 has been cited as a biomarker for increased insulin resistance in non-insulin dependent diabetes." (PMID 37671166, 2023).
breast carcinoma (1 paper, 2023). "ENPP5 mRNA expression was increased in human breast cancer patient samples, and significantly higher in human breast cancer cell lines compared to normal human breast cell line MCF-10A." (PMID 37352273, 2023). "It indicates that ENPP5 is upregulated in breast cancer oppositely to miR-126." (PMID 37352273, 2023).
triple-negative breast carcinoma (1 paper, 2023). An invasive breast carcinoma which is negative for expression of estrogen receptor (ER), progesterone receptor (PR), and human epidermal growth factor receptor 2 (HER2). "This is an interesting area of research, as ENPP5 has recently been proposed as a driver of triple-negative breast cancer, a major enzyme of the lysophosphatidic acid pathway." (PMID 37352273, 2023).
cancer (3 papers, 2021 to 2023). A tumor composed of atypical neoplastic, often pleomorphic cells that invade other tissues. "EDA, SEMA3G, ENPP5, EMX2, and OPCML were favorable factors and had low expression levels in ccRCC tissues, whereas PCDHGC3 was a risk factor and highly expressed in cancer tissues." (PMID 36505496, 2022). "Overexpression of L1 sequence in cancer blocked the depletion of ENPP5, a target gene of miR-126." (PMID 37352273, 2023). "The remaining signature genes, CPXM2, ENPP5, SAMD13, SLC52A1, ZNF682, ZNF835, ZNF571-AS1 and U91328.1, have not been related to carcinoma, yet." (PMID 33672117, 2021).
tumor (3 papers, 2012 to 2023). "The genes that have been highlighted by this analysis include mirror image polydactyly-1 (MIPOL1), a candidate tumour suppressor gene and ENPP5 (a closely-related molecule to ENPP2 (autotaxin))." (PMID 22311740, 2012). "Twenty candidate genes (84%) showed methylation in greater than 50% of primary tumor, including ADFP, FUZ, ZNF71, ENPP5, ZNF211, and ZNF14." (PMID 26544568, 2015).
ENPP5 also shares sentences with these, for which no sentence is quoted: colon cancers (1 paper); glioma (1); infection (1); insulin dependent diabetes (1); lung adenocarcinoma (1); lung carcinoma (1); movement disorder (1).